FGF2 (fibroblast growth factor 2)
Diseases named in the same sentence as FGF2 in open-access papers (continued):
Sharing a sentence is not in itself a finding about the gene and the disease.
Sepsis (22 papers, 2013 to 2025). Sepsis is defined as life-threatening organ dysfunction caused by a dysregulated host response to infection. "Specifically, research has shown that FGF2 can reduce capillary permeability and inflammation in sepsis and improve coagulation abnormalities associated with the disease." (PMID 39436561, 2024). "FGF2 has also been implicated in the attenuation of radiation-induced increase in intestinal permeability, which is considered an important cause of sepsis after WBI29,30." (PMID 29515101, 2018). "Collectively, these findings suggest that FGF2 supplementation confers protection against cardiac injury and preserves cardiac function during sepsis by mitigating inflammation, oxidative stress, and apoptosis." (PMID 41292702, 2025). "This mechanistic link between FGF2 and mitophagy represents a novel finding in the context of sepsis." (PMID 41292702, 2025). "Our research demonstrates that the protective effect of FGF2 on mitophagy in septic cardiomyopathy is mediated by FUNDC1, providing novel insight into the underlying mechanisms of sepsis-induced cardiac dysfunction." (PMID 41292702, 2025). "To investigate the in vivo role of FGF2 deficiency macrophages, we used a macrophage clearance and reconstruction model, in conjunction with CLP surgery, to induce sepsis and assess the impact of FGF2 deletion on septic ALI." (PMID 39436561, 2024). "Subsequent macrophage depletion and reconstitution experiments in sepsis mouse models have provided evidence that FGF2 KO macrophages aggravated sepsis-induced acute lung injury." (PMID 39436561, 2024). "A recent study showed that administration of recombinant FGF2 alleviated pulmonary vascular leakage and attenuated the inflammatory response in sepsis-induced ALI by stabilizing adherens junctions." (PMID 36969192, 2023). "Currently, there is only one clinical study that compares blood FGF-2 concentrations in 118 healthy control subjects with 18 sepsis patients." (PMID 37915587, 2023). "For instance, HS promotes reconstitution of the endothelial glycocalyx by regulating the activation of fibroblast growth factor 2 (FGF2)—FGF receptor 1 (FGFR1) signaling—which is suppressed during sepsis and via direct incorporation of HS into the glycocalyx." (PMID 37892576, 2023). "This study found that the median FGF-2 concentration in sepsis patients was significantly lower than that in healthy controls (25.7 vs. 37.7, P =0.0057)." (PMID 37915587, 2023). "We have previously shown that the combination of serum IL-18 and FGF-2 is a useful biomarker to discriminate between sepsis and adult-onset Still’s disease (AOSD)." (PMID 34654467, 2021). "The best combination of cytokines to distinguish AOSD from sepsis was found to be IL-18 (> 543 pg/mL) and FGF-2 (> 36 pg/mL), with high accuracy observed (sensitivity 100%, specificity 72.2%, and accuracy 93.8%)." (PMID 32381117, 2020). "Here, we conducted this study aiming to evaluate the therapeutic effect of FGF2 in sepsis-induced ALI." (PMID 33187467, 2020). "IL-18 and then FGF-2 were extracted as the most important cytokines for distinguishing AOSD from sepsis (mean decrease accuracy 17.2 and 11.4, respectively)." (PMID 32381117, 2020). "FGF2 was beneficial in sepsis-induced ALI by alleviating inflammation and attenuating endothelial permeability via P38/AKT/NF-κB pathways, which indicated that FGF2 is a new promising treatment for sepsis." (PMID 33187467, 2020). "In addition, the average value in the FGF2 KO group was significantly higher than that in the WT group in the sepsis model." (PMID 39436561, 2024). "Furthermore, in vivo experiments revealed that depletion of FGF2 in macrophages worsened sepsis-induced lung inflammation, lung vascular leak, and lung histological injury, accompanied by an increase in CD86-positive cells and apoptosis." (PMID 39436561, 2024). "Additionally, the expression of IL1β, TNFα, and IL6 in BALF from FGF2 KO mice was higher than that in WT mice in the sepsis model." (PMID 39436561, 2024).
Sepsis (continued). "Based on these preliminary results, we inferred that the NLRP3 inflammasome may play a partial role in the polarization of M1 macrophages in FGF2 knockout macrophages and sepsis-induced acute lung injury." (PMID 39436561, 2024). "Moreover, we corroborated the results of the repressed liver metabolic processes and enhanced the immune response in sepsis mice via RT-qPCR targeting the marker genes, such as Acaca, Acacb, Cyp7a1, FGF2, and A2m." (PMID 37512913, 2023). "Last, previous studies had proposed that PCT, IL-18 combined with fibroblast growth factor 2 (FGF 2) and modified Pouchot Score including elevated serum ferritin levels could be a useful diagnostic tool to distinguish AOSD and sepsis." (PMID 33868298, 2021). "We also eliminated endogenous macrophages using clodronate liposomes and administered FGF2 knockout or WT macrophages intravenously in conjunction with cecal ligation and puncture (CLP) surgery to induce sepsis." (PMID 39436561, 2024). "In conclusion, our study demonstrates that the measurement of FGF-2 and IL-18 levels in combination represents an effective biomarker for the differential diagnosis of AOSD from sepsis." (PMID 32381117, 2020). "Our study has now revealed that FGF2 regulates FUNDC1-related mitophagy via the AMPK pathway in the context of septic cardiomyopathy, providing a novel insight into the pathophysiology of sepsis-induced cardiac dysfunction." (PMID 41292702, 2025). "This is the first study to demonstrate that deletion of FGF2 in macrophages promotes macrophage polarization towards the M1 phenotype, enhances the expression of inflammatory mediators, and exacerbates lung pathology in CLP-induced sepsis." (PMID 39436561, 2024). "Thus, in the FMF group, FGF-2, GM-CSF, MIP-1β, and TNF-α form interrelated networks, whereas in the sepsis group, IFN-γ, TNF-α, IL-8, and MIP-1α form interrelated networks." (PMID 34654467, 2021). "Among the six cytokines that differed significantly between the sepsis and FMF groups, GM-CSF, VEGF, FGF-2, and IL-17A were significantly increased in the FMF group compared with the control group, and TNF-α and MIP-1β were significantly higher in the sepsis group than in healthy subjects." (PMID 34654467, 2021). "Thus, in the AOSD group, FGF-2, GM-CSF, IL-17, IL-18, and VEGF form interrelated networks, whereas in the sepsis group, IFN-γ, TNF-α, IL-8, IL-10, and IL-18 form interrelated networks." (PMID 32381117, 2020). "Although, consistent with previous reports, we did not observe serum FGF-2 levels to be elevated in patients with sepsis, no studies have measured serum FGF-2 levels in patients with AOSD." (PMID 32381117, 2020). "Determination of FGF-2 and IL-18 levels in combination may represent a biomarker for the differential diagnosis of AOSD from sepsis, based on the measurement of multiple cytokines." (PMID 32381117, 2020). "Multivariate classification followed by logistic regression analysis revealed that measurement of both FGF-2 and IL-18 could distinguish AOSD from sepsis with high accuracy (cutoff value for FGF-2 = 36 pg/mL; IL-18 = 543 pg/mL, sensitivity 100%, specificity 72.2%, accuracy 93.8%)." (PMID 32381117, 2020). "However, whether the FGF2 has a therapeutic effect in sepsis and ALI has never been reported." (PMID 33187467, 2020).
neuroblastoma (21 papers, 2010 to 2025). Neuroblastoma (NB) is the most common solid, extracranial childhood tumor. "TGF-β signalling has previously been linked to adult neurogenesis, FGF2-mediated neuroblastoma differentiation, and neuroblastoma cell invasiveness." (PMID 28187790, 2017). "AAV-mediated systemic delivery of human IFN-β (AAV-hIFN-β) in combination with low-dose cyclophosphamide showed anti-angiogenic activity with down regulation of VEGF and FGF-2 and also caused complete tumor regression in orthotopic retroperitoneal and disseminated models of neuroblastoma." (PMID 21876694, 2012). "In neuroblastoma models, FGF-2 mediated differentiation was dependent on HS-modified BG, specifically 2-O sulfated glucuronic and N-sulfated glucosamine and complex formation with FGF receptors and BG was GAG chain-dependent." (PMID 38360757, 2024). "By contrast, mouse OPCs doubled approximately every 7 dayswhen grown in 30% B104 neuroblastoma conditioned medium supplemented with FGF-2(B104CM+FGF-2) and in a 2% oxygen, nitrogen buffered environment." (PMID 34612709, 2021). "Recently, Microarray data of gene expression profiles suggested that MALAT1 promoted the secretion of fibroblast growth factor 2 (FGF2) in neuroblastoma cells under hypoxic conditions." (PMID 28418892, 2017). "Microarray-based differential gene expression analysis showed that one of the genes most significantly down-regulated following MALAT1 suppression in human neuroblastoma cells under hypoxic conditions was fibroblast growth factor 2 (FGF2)." (PMID 26848616, 2016). "Taken together, our data suggest that up-regulation of MALAT1 expression in human neuroblastoma cells under hypoxic conditions increases FGF2 expression and promotes vasculature formation, and therefore plays an important role in tumor-driven angiogenesis." (PMID 26848616, 2016). "RT-PCR and immunoblot analyses confirmed that MALAT1 suppression reduced FGF2 expression, and Enzyme-Linked Immunosorbent Assays revealed that transfection with MALAT1 siRNAs reduced FGF2 protein secretion from neuroblastoma cells." (PMID 26848616, 2016). "4-HPR through inhibition of both VEGF and FGF-2 induced endothelial cell proliferation to downregulate angiogenesis in neuroblastoma." (PMID 21876694, 2012). "VEGF, FGF-2, PDGF, SCF, and their cognate receptor tyrosine kinases are strongly implicated in angiogenesis in solid tumors like neuroblastoma." (PMID 21876694, 2012). "Regarding neural cell populations, the activation of P2X7R in astrocytes inhibits fibroblast growth factor 2-induced proliferation and promotes the differentiation of neuroblastoma N2a cells via the regulation of the Ca2+⁄calmodulin-dependent kinase II signalling cascade." (PMID 33427974, 2021). "MALAT1 promotes the upregulation of Fibroblast Growth Factor 2 (FGF2) mRNA and protein expression in neuroblastoma cells and enhances FGF2 secretion into the extracellular fluid." (PMID 40104501, 2025). "The ccp1 transcript was up-regulated upon FGF2 stimulation in primary cortical neuron culture (CNC) derived from mouse embryonic telencephalon at embryonic day 14.5 (E14.5) and in neuroblastoma cell line, SK-N-SH." (PMID 21118521, 2010). "There is also evidence to suggest CCDC115 can disrupt cell proliferation and apoptosis in neuroblastoma cells of the brain via the FGF2 and MAPK pathway, where FGF2 has previously been shown to increase migration, invasion and epithelial to mesenchymal transition in PC cell lines." (PMID 29890952, 2018). "In the human neuroblastoma cell line, SK-N-MC, it was found that fibroblast growth factor-2 (FGF-2) can induce Id1 expression at both the mRNA and protein levels; the inhibition of Id1 expression results in an accumulation of FGF-2-treated cells at the G2/M stage and postpones cell death." (PMID 32708313, 2020).
Parkinson disease (21 papers, 2007 to 2025). A progressive degenerative disorder of the central nervous system characterized by loss of dopamine producing neurons in the substantia nigra and the presence of Lewy bodies in the substantia nigra and locus coeruleus. "For example, increasing the concentration of FGF2 protein appears to offset the functional outcome of neonatal damage to the motor cortex, and the neuroprotective effect of nicotine in animal models of Parkinson disease is associated with its ability to up-regulate fgf2 expression." (PMID 17589599, 2007). "In SH-SY5Y cells, overexpression of FGF2 plays a protective role in Parkinson’s disease by inhibiting apoptosis and promoting autophagy." (PMID 35784556, 2022). "In a model of Parkinson's disease, the combined application of growth factors such as epidermal growth factor and fibroblast growth factor 2 was sufficient to enhance migration of neuroblasts to the striatum; however it did not result in neuronal maturation." (PMID 20836877, 2010). "In particular, in Parkinson disease, degeneration begins in the brain stem, the region in which we found reduced fgf2 expression after neonatal organophosphate exposure." (PMID 17589599, 2007). "We conclude that hBM MSC can be coaxed to differentiate efficiently into dopaminergic neurons in the presence of a very simple media cocktail containing only one main inducer like FGF2 and thus contribute towards cellular therapy in Parkinson's and other related disorders." (PMID 25248378, 2014). "In addition, FGF2/FGFR1 signaling could regulate inflammation of hippocampus to exert a positive effect on some neurodegenerative diseases such as Parkinson’s disease, Alzheimer’s disease, multiple sclerosis, and traumatic brain injury." (PMID 30210273, 2018). "Moreover, FGF-2 has physiological relevance for dopaminergic (DA) neurons of the nigrostriatal system and FGF-2 depletion might be related to Parkinson's disease." (PMID 21876757, 2011).
cervical cancer (20 papers, 2002 to 2025). A primary or metastatic malignant neoplasm involving the cervix. "The PPI network showed that IL6, VEGFA, and FGF2 are the key targets of seabuckthorn polysaccharides in the prevention and treatment of cervical cancer." (PMID 36845055, 2023). "By acting as ceRNA, lncRNA HOXD-AS1 promotes expression level of fibroblast growth factor 2 (FGF2) in mediating cervical cancer progression." (PMID 35773731, 2022). "RHPN1 antisense RNA1 (RHPN1-AS1) upregulates the expression of fibroblast growth factor 2 (FGF2), a potent regulator of mitogenic activity, by binding to miR-299–3p, thereby promoting cervical cancer cell proliferation." (PMID 32928281, 2020). "Additionally, FGF2 suppression markedly impedes the proliferative capacity and invasiveness of cervical cancer cells." (PMID 39091947, 2024). "Notably, FGF2 facilitates cell migration and invasion in some cancers like breast, pancreatic and cervical cancers." (PMID 32977766, 2020). "Furthermore, we uncovered the FGF2-NANOG molecular axis as a downstream component of API5 signaling that is conserved in cervical cancer patients, as well as an in vivo zebrafish model." (PMID 28092370, 2017). "Furthermore, we uncovered the FGF2-NANOG molecular axis as a downstream component of API5 signaling that is conserved in cervical cancer patients." (PMID 28092370, 2017). "FGF-2 and its mRNA are reportedly elevated in cervical cancers in humans." (PMID 18232728, 2008). "Moreover, a study of human cervical carcinomas employing in situ hybridization previously reported that FGF-2 was expressed by stromal fibroblasts." (PMID 18232728, 2008). "The molecular docking analysis of the 306 differential proteins with known cervical cancer–related targets identified intersecting proteins within the PI3K/AKT signaling pathway: PIK3R2, GRB2, MAPK1, FGF2, and PRKCA." (PMID 40733070, 2025). "Importantly, FGF2 expression was positively correlated with expression of API5 and NANOG in cervical cancer tissue, validating the biochemical pathway that we proposed." (PMID 28092370, 2017). "Finally, as in HPV/E2 mice, FGF-2 and PDGF receptors were expressed in the stroma of human cervical cancers whereas PDGF was expressed in the cancer cells." (PMID 18232728, 2008). "Notably, FGF-2, PDGF receptor-α, and PDGF receptor-β were found to be expressed in the stroma of 9/11, 12/12, and 9/9 cervical cancers, respectively, whereas expression in the overt squamous cancer cells was not consistently detected, the exception being a single case that expressed PDGF receptor-β." (PMID 18232728, 2008).
myopia (20 papers, 2007 to 2025). "The second aim was to test for any association between single nucleotide polymorphisms (SNPs) of FGF2 and high myopia in a Chinese population residing in Taiwan." (PMID 22393273, 2012). "We also tested for the association between six tSNPs at the FGF2 gene and high myopia in a Chinese population residing in Taiwan." (PMID 22393273, 2012). "This study measured retinal FGF2 gene expression in an animal model and also tested for the association between single nucleotide polymorphisms (SNPs) in FGF2 and high myopia." (PMID 22393273, 2012). "SNPs were also analyzed in genes where their expression pattern or their association with syndromes conveys myopia as part of the phenotype (FGF2, BDNF, COL2A1, COL18A1, and PAX6)." (PMID 17653045, 2007). "There was some evidence of association in the TDT analysis between myopia and over-transmission of the common allele of the FGF2 SNP rs1048201 (p=0.01)." (PMID 17653045, 2007). "GROa may be associated with increased myopia risk; FGF2, GROa, and IL-1RA may be upstream causes of cataract." (PMID 40687727, 2025). "Given that a change of retinal FGF2 expression was associated with myopia development in the animal study, we then tested whether genetic variants of FGF2 were associated with high myopia in human subjects." (PMID 22393273, 2012). "Growth factors like IGF1 and FGF2 regulate ocular growth, contributing to myopia, and TGF-β family members are important for early eye development and myopia pathogenesis." (PMID 40110040, 2025). "With form-deprivation myopia, fgf2 expression was reported to be down-regulated in the chick sclera but up-regulated in guinea pig retinae." (PMID 39607017, 2024). "The Fibroblast growth factor-2 (FGF-2) was reported involved in scleral remodeling in myopia models." (PMID 38012225, 2023). "Recent studies have shown that FGF2 plays an important role in the treatment of neuroretinal degeneration, myopia, vitreous lesions and in the protection of photoreceptors from oxidative damage." (PMID 31619580, 2019). "This network was composed primarily of genes involved in immune-mediated ECM remodeling, and included connections with many intermediate genes that have been strongly linked to myopia in previous targeted studies (e.g. MMP2, TGFB1, TGFB2, FGF2, INS, and IGF2)." (PMID 28852117, 2017). "Fibroblast growth factor-2 (FGF2) has been implied in the development of myopia according to previous studies investigating FGF2 in the sclera and retinal pigment epithelium." (PMID 22393273, 2012). "The relationship between the FGF2 expression pattern and myopia is inconsistent among previous studies." (PMID 22393273, 2012). "Since atropine has been demonstrated to retard myopia progression in humans, their FGF2 expression pattern is unexpected and hard to explain (personal communication with the correspondent author of the study)." (PMID 22393273, 2012). "We used the form deprivation to induce myopia in the guinea pigs and compared retinal FGF2 expression levels among the FDM eyes, fellow eyes of the experimental animals and normal eyes of the control animals." (PMID 22393273, 2012). "The first aim of the present study was to measure FGF2 gene expression during the development of myopia in the mammals." (PMID 22393273, 2012). "Basic fibroblast growth factor (FGF-2) has been shown to inhibit form deprivation myopia in the chick." (PMID 17653045, 2007). "None of the tested SNPs are significantly associated with high myopia, which suggests that FGF2 genetic variants are unlikely to influence individual difference of myopia susceptibility." (PMID 22393273, 2012). "We identified a significant change of FGF2 expression in the FDM eyes but FGF2 genetic variants are unlikely to influence susceptibility to myopia." (PMID 22393273, 2012). "Although animal studies have revealed FGF2 as a candidate gene, the relationship between genetic polymorphisms of FGF2 and myopia has not been extensively investigated." (PMID 22393273, 2012).